ACHE (acetylcholinesterase (Yt blood group))
Diseases named in the same sentence as ACHE in open-access papers (continued):
Sharing a sentence is not in itself a finding about the gene and the disease.
Cerebral atrophy (1 paper, 2017). Atrophy (wasting, decrease in size of cells or tissue) affecting the cerebrum. "Cerebral atrophy was found to be regulated by two key players— Transferrin as well as ACHE." (PMID 28731430, 2017).
chronic fatigue syndrome (1 paper, 2021). "Large amounts of organophosphorus pesticides can inhibit acetylcholinesterase (AChE) in the central and peripheral nervous systems and promote an increase in acetylcholine, which can lead to nausea, headache, psychosis, depression, memory loss, chronic fatigue syndrome, and respiratory problems." (PMID 34790174, 2021).
Creutzfeldt-Jakob disease (1 paper, 2015). "Indeed, reduced AChE activity in lumbar CSF samples and altered AChE glycosylation in the brain and CSF samples of patients with Creutzfeldt-Jakob disease (CJD) have been observed." (PMID 25853328, 2015).
demyelinating disease (1 paper, 2024). A broad group of disorders that affect the myelin sheaths that cover the neurons. "In the context of drug repurposing, the myelin-promoting properties of donepezil, along with its dual inhibitory activity against AChE and activation of Sig-1R, render it as a promising candidate for the management of demyelinating diseases." (PMID 38558359, 2024).
dry eye (1 paper, 2023). "The cognitive function, working memory, dry eye, AChE, MAO, MAO-A, MAO-B, and GABA-T activities, BDNF, HAC, HDAC, and DNMT activities, pH, and amount of lactic acid-producing bacteria, particularly Lactobacillus and Bifidobacterium spp." (PMID 37630690, 2023).
erectile dysfunction (1 paper, 2024). Persistent or recurrent inability to achieve or to maintain an erection during sexual activity. "Application: prospects for development of an additive or ingredient for natural remedy for erectile dysfunction;Extraction procedure: SD;Chemical composition: GC–MS;Biological characterisation: PDE5, ACE, AChE, and ARG2 inhibition assays." (PMID 39407589, 2024).
experimental autoimmune encephalomyelitis (1 paper, 2016). An autoimmune demyelinating disease of the central nervous system that is produced experimentally in animals by the injection of homogenized brain or spinal cord in Freund's adjuvant. "In experimental autoimmune encephalomyelitis mice (EAE), the main MS animal model, the use of AChE inhibitors causes a significant reduction of CNS lymphocyte infiltrates, confirming a role for ACh even in the modulation of central nervous system inflammation." (PMID 27916909, 2016).
fecal incontinence (1 paper, 2018). Involuntary passage of stool from the rectum. "In patients with fecal incontinence responding to SMDCs treatment, the improvement of clinical symptoms was positively linked with the AChE activity of the SMDCs injected." (PMID 29566057, 2018). "Most convincingly, our results demonstrate a link between clinical efficacy and the AChE activity of the SMDCs preparations used for the treatment of fecal incontinence." (PMID 29566057, 2018). "Most convincingly, our results raise evidence of a link between clinical efficacy and the AChE activity of in vitro differentiated SMDC preparations used in the clinic for the treatment of fecal incontinence." (PMID 29566057, 2018). "In the future, effective dose definition of SMDCs for fecal incontinence treatment might be performed by defining an AChE activity predictive for clinically significant treatment outcome." (PMID 29566057, 2018). "AChE activity of in vitro differentiated SMDCs was correlated with CD56 expression, fusion index, cell number, cell doubling numbers, differentiation markers and compared to the clinical efficacy in patients treated with SMDCs against fecal incontinence." (PMID 29566057, 2018).
Fever (1 paper, 2021). Body temperature elevated above the normal range. "The detected activity of AChE in the fever group indicates that it was not degraded in the target tissue during behavioural fever, and this molecule could become available to interact with Chrna7, thus inhibiting the release of inflammatory factors." (PMID 34445566, 2021).
fluorosis (1 paper, 2023). "Furthermore, our results indicated that the changes in learning, memory, and cognitive function of the fluorosis rats were related to AchE and ChAT activity and were influenced by the fluoride exposure dose." (PMID 37711250, 2023).
fungal infection (1 paper, 2025). "Biochemical analyses revealed that fungal infection significantly inhibited the activity of the key antioxidant enzyme SOD in the host, while activities of POD, CAT, and detoxification enzymes (P450, CarE, AChE, and GSTs) were significantly increased." (PMID 41009055, 2025). "Differences in AChE and CYP450 responses compared with other host–pathogen systems, such as Spodoptera frugiperda and Aphis citricola, may reflect species-specific metabolic and neurophysiological adaptations to fungal infection." (PMID 41009055, 2025).
Glucose intolerance (1 paper, 2011). Glucose intolerance (GI) can be defined as dysglycemia that comprises both prediabetes and diabetes. "However, since IDFP does not inhibit AChE in vivo, IDFP, and perhaps other OPs, produce glucose intolerance via CB1 and AChE independent pathways." (PMID 22073164, 2011).
head and neck carcinoma (1 paper, 2015). A carcinoma that arises from the head and neck region. "Since smoking is strongly associated with head and neck cancer, correlation between tobacco exposure and level of expression of AChE and BChE mRNAs was assessed." (PMID 25956553, 2015). "Contrary to AChE, BChE was found to be up-regulated in head and neck carcinoma as judged by the negligible level of BChE mRNA in ANCT and its strong increase in HNSCC." (PMID 25956553, 2015). "Our results suggest that the low AChE activity in HNSCC can be used to predict survival in patients with head and neck cancer." (PMID 25956553, 2015). "Moreover, the drop of AChE and BChE activities in head and neck cancers and the differences between ANCT and HNSCC pieces in AChE, BChE, nAChR and mAChR mRNA levels lent strong support to the notion that a non-neuronal cholinergic system may be involved in head and neck malignancy." (PMID 25956553, 2015).
Headache (1 paper, 2023). Cephalgia, or pain sensed in various parts of the head, not confined to the area of distribution of any nerve. "Headache and forgetfulness/lack of concentration were significantly associated with the inhibition of the AChE enzyme (p-value 0.0146 and <0.0001)." (PMID 37252928, 2023).
hydronephrosis (1 paper, 2016). Collection of urine in the renal pelvis that results in dilatation of the renal pelvis and calyces. "Whole-mount AChE staining showed that number of ENS cells was decreased in the Nedl1−/−;Nedl2−/− mice and HE staining showed hydronephrosis in kidneys." (PMID 27119228, 2016).
Hyperammonemia (1 paper, 2025). An increased concentration of ammonia in the blood. "Moreover, our results indicated a correlation between hyperammonemia and elevated nitric oxide (NO) and acetylcholinesterase (AChE) activity." (PMID 39806460, 2025).
immune deficiency (1 paper, 2021). "More recently, expression of three different types of the AChE mRNAs has been detected in human peripheral blood lymphocytes and changes in lymphocyte AChE activity were related to cell dysfunction reflecting immune deficiency." (PMID 33921376, 2021).
immunotoxicity (1 paper, 2023). "The recognized toxic mechanism of CPF is that it can inhibit the activity of acetylcholinesterase (AChE), resulting in severe adverse impacts on non-target organisms, e.g., nephrotoxicity, immunotoxicity, genotoxicity, reproductive, and developmental toxicity." (PMID 37629125, 2023).
infertile (1 paper, 2023). "The purpose of the study was to find the possible impact and association of acetylcholinesterase, ACHE gene variant rs 17228602, and pro-inflammatory cytokines in clinically diagnosed infertile males." (PMID 37027384, 2023). "In addition, an association of ACHE gene SNP rs17228602 was evident with the infertile males." (PMID 37027384, 2023). "The elevated AChE activity in infertile males as observed in the present study is suggestive of low-grade systemic inflammation." (PMID 37027384, 2023). "A significantly higher level (p≤0.001; independent sample t-test) of AChE enzyme activity was found in the infertile group (0.64±0.26 mU/μmol Hb, 95% CI 0.56–0.72; n = 42) as compared to non-infertile cohort (0.29±0.28 mU/μmol Hb, 95% CI 0.21–0.36; n = 50)." (PMID 37027384, 2023). "In the present study, the possible role of AChE activity and pro-inflammatory cytokines were examined in infertile males that are clinically diagnosed and investigated the tentative association of ACHE gene SNP rs 17228602 with male infertility." (PMID 37027384, 2023). "This study will help in understanding unexplained infertility cases with new approaches, and open a new direction for further studies like miRNA regulating AChE and cytokines in infertile, ultimately may lead to the development of a novel diagnostic marker for male infertility." (PMID 37027384, 2023). "Genotypes and allelic frequency in AChE gene SNP rs 17228602 in non-infertile and infertile males." (PMID 37027384, 2023). "AChE enzyme was found to be significantly elevated in infertile than non-infertile males." (PMID 37027384, 2023).
intestinal neuronal dysplasia (1 paper, 2015). "There was one case of HD, redesignated as intestinal neuronal dysplasia, where the alert was sounded by AChE histochemistry." (PMID 26631177, 2015).
irritable bowel syndrome (1 paper, 2021). Irritable bowel syndrome (IBS) is a chronic functional condition of the lower gastrointestinal (GI) tract characterized by abdominal pain or discomfort and disordered bowel habit (diarrhea, constipation, or fluctuation between the two). "In two independent studies, serum AChE levels and CS were substantially higher in patients with irritable bowel syndrome (IBS), whereas CS was significantly lower in IBD patients." (PMID 33936095, 2021).
language disorder (1 paper, 2021). A category of disorders characterized by an impairment in the development of an individual's language capabilities, which is in contrast to his/her non-verbal intellect. "Acetylcholinesterase (AChE) has been regarded as an attractive target in the treatment of Alzheimer’s disease (AD), the most common neurodegenerative disease in old age that is characterized clinically by progressive memory loss, cognitive dysfunction, language disorders, and personality changes." (PMID 35178381, 2021).
leukocytosis (1 paper, 2023). "Increased AChE activity may be associated with concurrent leukocytosis following traumatic injury." (PMID 36830636, 2023).
liver fibrosis (1 paper, 2021). "In addition, among all common targets for RGGs and liver fibrosis, ESR1, ESR2, AR, ACHE, CYP19A1, and AKR1B1 have a high degree of interaction with other targets and some active compounds." (PMID 35115923, 2021).
Machado-Joseph disease (1 paper, 2024). "Research on the potential use of AChE inhibitors for the treatment of Machado-Joseph disease (MJD)/Spinocerebelar Ataxia 3 (SCA3), an inherited neurodegenerative disorder characterized mostly by motor impairments, is limited." (PMID 38404918, 2024). "However, there has been limited research on the potential use of AChE inhibitors for the treatment of Machado-Joseph disease (MJD)/Spinocerebellar Ataxia 3 (SCA3), in spite of the positive results using AChE inhibitors in patients with other inherited ataxias." (PMID 38404918, 2024).
male infertility (1 paper, 2023). The inability of the male to effect fertilization of an ovum after a specified period of unprotected intercourse. "Molecular analysis of ACHE gene SNP rs17228602 revealed a significant (p = 0.000) association with male infertility." (PMID 37027384, 2023). "Other variants of ACHE and the association of miRNA for the regulation of AChE in male infertility are suggested for further insight." (PMID 37027384, 2023). "AChE enzyme and ACHE gene SNP rs17228602 are involved in male infertility, especially in primary infertility, oligospermia, and oligoasthenospermia." (PMID 37027384, 2023). "The study concludes and speculates that AChE plays role in the pathogenesis of male infertility through the modulation of inflammatory pathways." (PMID 37027384, 2023). "In addition, research on cholinergic-anti-inflammatory pathways and AChE-regulating miRNA may provide a better understanding of idiopathic and unexplained cases of male infertility." (PMID 37027384, 2023).
malignant brain tumors (1 paper, 2010). "Although serum AChE levels were a routine investigation in malignant brain tumors, this was not a routine in other neurological conditions (hospitalized controls)." (PMID 21461159, 2010).
migraine (1 paper, 2017). "The inhibitor of AChE neostigmine did not change the firing per se but induced nociceptive activity, sensitive to d-tubocurarine, after pretreatment of meninges with the migraine mediator CGRP." (PMID 28496430, 2017).
motor neuron degeneration (1 paper, 2026). "Decreased acetylcholine release because of motor neuron degeneration, as well as decreased AChE activity in muscle and cerebrospinal fluid, has previously been reported in ALS patients." (PMID 41397872, 2026).
multiple system atrophy (1 paper, 2016). Multiple system atrophy (MSA) is a neurodegenerative disorder characterized by autonomic failure (cardiovascular and/or urinary), parkinsonism, cerebellar impairment and corticospinal signs with a median survival of 6-9 years. "In other atypical parkinsonisms such as multiple system atrophy, cortical AChE activity decreases have been found to be similar to those seen in PD patients (−14.6 % and −15.3 %, respectively)." (PMID 26984612, 2016). "Thalamic AChE is significantly reduced in progressive supranuclear palsy (PSP) and multiple system atrophy, whilst it is not affected in PD." (PMID 26984612, 2016).
myeloid leukemia (1 paper, 2019). A clonal proliferation of myeloid cells and their precursors in the bone marrow, peripheral blood, and spleen. "All isolated compounds were tested for acetylcholinesterase (AChE) inhibitory activity and cytotoxic activity against human myeloid leukemia cell line (K562)." (PMID 30736275, 2019).
nasopharyngeal carcinoma (1 paper, 2021). A carcinoma arising from the nasopharyngeal epithelium. "The in vitro bioassay and in silico docking study revealed compound 4 to be a potential anti-nasopharyngeal cancer drug and a moderate AChE inhibitor." (PMID 34940700, 2021).
neurocysticercosis (1 paper, 2020). "Notably, the reported AChE activity of tetrathyridia of Mesocestoides corti, another popular model parasite for neurocysticercosis research, is far greater than that which we report for both T. crassiceps and T. solium." (PMID 33347447, 2020).
neuroendocrine disorder (1 paper, 2017). A disease or disorder that affects the neuroendocrine gland, any of the organized aggregations of cells that function as secretory or excretory organs and that release hormones in response to neural stimuli. "Our study suggests that AChE inhibitors not capable of crossing the BBB might potentially be used in the therapy of inflammatory induced neuroendocrine disorders." (PMID 28894751, 2017).
neurovascular disorder (1 paper, 2023). A disorder of the nervous system related to a vascular etiology. "The various medicinal plants and their constituents (Palm-Oil-Derived BC, rutin, alpha-napthoflavone, and curcumin) were proven to ameliorate neurovascular disorders via AChE inhibitory actions without toxic effects due to their multitargeted actions and antioxidant potentials." (PMID 37298835, 2023).
non-small cell lung carcinoma (1 paper, 2015). A group of at least three distinct histological types of lung cancer, including non-small cell squamous cell carcinoma, adenocarcinoma, and large cell carcinoma. "In this regards, it is worth mentioning the reported tumour-suppressor activity that synaptic AChE (targeted by miRNA-212) plays in non-small cell lung cancer." (PMID 25956553, 2015).
Opsoclonus (1 paper, 2024). "The hypothesized pathophysiology was that inhibition of AChE caused by OPPs, induced a high level of synaptic cleft acetylcholine in the tectal/pretectal areas and in the midbrain tegmentum, thus causing opsoclonus." (PMID 38737300, 2024).
osteosarcoma (1 paper, 2019). A usually aggressive malignant bone-forming mesenchymal neoplasm, predominantly affecting adolescents and young adults. "Other studies also showed proline-rich membrane anchor-linked acetylcholinesterase (AChE), a special form of AChE in MG63 osteosarcoma and primary osteoblast cells, increased in flavonoid-induced osteoblast differentiation." (PMID 31440007, 2019).
perinatal asphyxia (1 paper, 2021). A disorder caused by a lack of blood flow or gas exchange to or from the fetus in the period immediately before, during, or after the birth process. "Researchers found that MCPS promoted long-term learning and memory in perinatal asphyxia (PA) pups by decreasing oxidative damage and acetylcholinesterase (AChE) activity in the brain, and increasing the expression of p-CREB and brain-derived neurotrophic factor (BDNF) in the hippocampus." (PMID 34504861, 2021).
periodontal disease (1 paper, 2025). "In summary, this study reports the role of the AChE‐ACh‐α7nAChR axis in the modulation of inflammatory responses and neuroimmune interactions in periodontal disease in a sleep deprivation model and EA targeting this pathway." (PMID 40810704, 2025).
periodontitis (1 paper, 2025). An acute or chronic inflammatory process that affects the tissues that surround and support the teeth. "Finally, this study elucidates the critical role of the “oral‐brain axis” in the occurrence, development, and treatment of periodontitis associated with systemic diseases, as well as the pivotal role of the cholinergic pathway (AChE, ACh, α7nAChR) in this pathology." (PMID 40810704, 2025). "Sleep deprivation (SD) exacerbates ligature‐induced periodontitis (LIP) through the trigeminal nerve‐periodontal neuroimmune pathway mediated by the acetylcholinesterase (AChE)‐acetylcholine (ACh)‐α7 nicotinic receptor (α7nAChR) axis." (PMID 40810704, 2025). "Clinical validation in periodontitis patients with poor sleep (PSQI≥5) further demonstrated salivary/serum ACh reduction and AChE upregulation, supporting EA‐mediated α7nAChR activation as a novel neuroimmunomodulatory for comorbid sleep‐periodontitis conditions." (PMID 40810704, 2025). "Therefore, SD exacerbates periodontitis via the AChE‐ACh‐α7nAChR axis‐mediated trigeminal‐periodontal neuroimmune pathway, whereas EA partially reverses this pathology by targeting macrophage α7nAChR." (PMID 40810704, 2025). "Finally, due to the lack of direct genetic manipulation, real‐time monitoring of ACh dynamics, and unresolved upstream regulatory mechanisms, the role of the AChE‐ACh‐α7nAChR axis in periodontitis remains incompletely elucidated." (PMID 40810704, 2025). "Our data show that SD inhibits the cholinergic anti‐inflammatory pathway and thus periodontitis by increasing trigeminal ganglion‐derived AChE in periodontal tissues, decreasing ACh binding to α7nAChR, while EA activates the cholinergic anti‐inflammatory pathway and partially reverses this effect." (PMID 40810704, 2025). "Collectively, these findings suggest that SD may exacerbate periodontitis by down‐regulating α7nAChR on peripheral macrophages and up‐regulating AChE in the trigeminal ganglion." (PMID 40810704, 2025).
plague (1 paper, 2017). Plague is a severe bacterial infection caused by the gram-negative bacterium Yersinia pestis. "Reports suggest that AChE plays a key role during the early development of senile plague, as was revealed by the finding that AChE accelerates β-amyloid peptide (Aβ) deposition." (PMID 29283428, 2017).